GRPR (gastrin releasing peptide receptor)
Diseases named in the same sentence as GRPR in open-access papers (continued):
Sharing a sentence is not in itself a finding about the gene and the disease.
breast carcinoma (continued). "Breast cancer overexpresses somatostatin receptors (SSTR), vasoactive intestinal peptide receptors (VIPR), the GRPR, and NPY(Y1)R." (PMID 32751666, 2020). "The agent was shown to be taken up into PCa PC3 and breast cancer MCF7 and MDA-MB231 cells to a significantly higher extent than the monospecific GRPR-targeting reference peptide (up to fivefold after 24 h) and further to be able to enter the nucleus." (PMID 32751666, 2020). "Another GRPR antagonist, RM2, was labeled with 68Ga and used for the PET/CT pre-treatment staging of patients with primary breast carcinoma already confirmed by biopsy." (PMID 31652624, 2019). "A study comparing a GRPR targeting radiotracer and 18F-FDG for primary staging or for restaging recurrent breast cancer would be appreciated." (PMID 30645633, 2019). "A study comparing a GRPR targeting radiotracer and 18F-FDG for primary staging and for restaging recurrent breast cancer is clearly needed." (PMID 30645633, 2019). "For example, breast cancer has been shown to concomitantly and complementarily overexpress the neuropeptide Y receptor subtype 1 (NPY(Y1)R) as well as the gastrin-releasing peptide receptor (GRPR)." (PMID 29973529, 2018). "The gastrin releasing peptide receptor (GRPR) and the somatostatin receptor 2 (SSTR2) are overexpressed on primary breast cancer (BC), making them ideal candidates for receptor-mediated nuclear imaging and therapy." (PMID 28107508, 2017). "Therefore, 99mTc-RGD-BBN may have the potential to make up for the deficiency of 99mTc-3P4-RGD2 in the detection of breast malignant tumors with integrin αvβ3 negative expression but GRPR positive expression." (PMID 25849333, 2015). "Gastrin releasing peptide receptor (GRPR)-directed radiopharmaceuticals for targeted radionuclide therapy may be a very promising addition in prostate and breast cancer patient management." (PMID 39825204, 2025). "Particularly, the 18F-equipped variant was tested on T47D and MDA-MB-435 tumor cells (human breast cancer cell lines) showing higher uptake on the T47D cells than on the MDA-MB-435 tumor cells, maybe due to the higher GRPR expression of the T47D cells." (PMID 40869454, 2025). "In addition to breast cancer, SAR-BBN PET-CThas the potential to be exploited in the theranostic management ofprostate cancer, due to its high expression of GRPR." (PMID 39895089, 2025). "The results from other ongoing clinical trials are eagerly awaited, in particular the evaluation of the theranostic couple [68Ga]Ga/[177Lu]Lu-NeoBOMB1 in patients with GRPR-expressing malignancies, including ER-positive/HER2-negative breast cancer led by Novartis." (PMID 38020178, 2023). "Consequently, this new option was almost immediately investigated in the field of BBN-like radioligands, directed to the gastrin-releasing peptide receptor (GRPR) detected in many frequently occurring tumors, especially in prostate and mammary carcinoma." (PMID 37242457, 2023). "Likewise, a high level of gastrin-releasing peptide receptor (GRPR) was found in various malignancies including prostate and breast cancers, as well as in gliomas." (PMID 36612012, 2022). "Several other promising targets in the HER2 subtype of breast cancer such as HER3, GRPR, and vitamin B12 offer additional options for targeted therapy, with their respective companion diagnostic imaging agents readily available for assessing target engagement or monitoring response to treatment." (PMID 33986665, 2021). "Besides the classic breast cancer targets, such as ER, PR, HER2, EGFR, and recently, GRPR, other targets such as FA and nucleolin have also shown some promise for theranostics of breast cancer." (PMID 33986665, 2021). "Thus, a GRPR- or NPY(Y1)R-monospecific peptide binder, irrelevant if monovalent or multivalent, can only address a portion of breast cancer lesions." (PMID 32751666, 2020).
breast carcinoma (continued). "The dual integrin αvβ3 and GRPR targeting 99mTc-RGD-BBN showed an excellent ability to detect breast cancer without clinically safety problems." (PMID 25849333, 2015). "Moreover, over-expression of GRPR was reported in other cancers, among the most relevant for use of a GRPR targeting radiotherapy are gastrinomas (about 100% express GRPR), gastrointestinal stromal tumors (GIST, about 85%) and estrogen receptor positive breast cancer (over 80%)." (PMID 38366299, 2024). "Out of these, the GRPR and the NPY(Y1)R are of particular interest for the development of radiolabeled heterobivalent peptidic agents as they are overexpressed in ≈75% and 66–85% of all breast cancer lesions, respectively, but only to an insignificant amount on healthy breast tissue." (PMID 32751666, 2020). "The PET tracer-based GRPR radioantagonist 68Ga-DOTA-p-aminomethyl aniline-diglycolic acid-D-Phe-Gln-Trp-Ala-Val-Gly-His-Leu-NHEt (68Ga-SB3) has shown excellent tumor localizing efficacy and pharmacokinetics in animals and patients with prostate and breast cancers." (PMID 33335885, 2020). "Although a direct correlation of GRPR-status and estrogen receptor expression could not be unequivocally demonstrated in the cell lines of this latest study, such a relationship could be established in biopsy specimens from breast cancer patients." (PMID 29137110, 2017).
lung carcinoma (23 papers, 2009 to 2025). "Specific examples, ARAF1 and ELK1, have been previously identified as oncogenes in testicular cancers with X-chromosome amplifications, and GRPR has been associated with an increased risk of lung cancer in females." (PMID 37759468, 2023). "In turn, the Xq22 region harbors several putative tumors suppressor genes which are inactivated by mutations in lung cancer cell lines and primary tumors (i.e. GRPR, VEGFD,and MID1)." (PMID 25415227, 2015). "Detection of GRPR mRNA in bronchial tissues was significantly associated with presence of lung cancer (O.R = 3.85; 95% CI = 2.37-6.25) (All Subjects)." (PMID 22296774, 2012). "The result of this study highlights GRPR overexpression in normal epithelial mucosa as a candidate risk factor for lung cancer, especially in those with limited tobacco exposure." (PMID 22296774, 2012). "Since GRPR stimulation induces proliferative effects in bronchial cells, it is possible that activation of this pathway is a risk factor for lung cancer separate from that of tobacco exposure." (PMID 22296774, 2012). "Our new findings reported here indicate that in a prospectively collected lung cancer case-control population, GRPR expression in at-risk upper aerodigestive mucosa was significantly associated with lung cancer." (PMID 22296774, 2012). "Despite these limitations, a high degree of association between detectable GRPR expression in normal bronchial tissue and lung cancer was demonstrated in the case-control population even after adjusting for sex and age." (PMID 22296774, 2012). "Bronchial GRPR expression was significantly associated with lung cancer (OR = 4.76; 95% CI = 2.32-9.77) in a multivariable logistic regression (MLR) model adjusted for age, sex, smoking status and pulmonary function." (PMID 22296774, 2012). "We evaluated the association between GRPR mRNA expression in purified cultured normal bronchial epithelial cells and the presence of lung cancer." (PMID 22296774, 2012). "Evaluation of association between GRPR broncial expression and demographic and risk factors stratified by lung cancer case status." (PMID 22296774, 2012). "Even after controlling for possible confounding effects of age, sex, smoking status and pulmonary function expression of GRPR in normal bronchial epithelium remained significantly associated with lung cancer (O.R. = 4.76; 95% CI = 2.32-9.77) (All Subjects)." (PMID 22296774, 2012). "Overexpression of gastrin-releasing peptide-receptors (GRPR) have been associated with many cancerous conditions such as ovarian, breast, prostate and lung cancer." (PMID 22198535, 2011). "We undertook a case-control study to determine whether elevated GRPR mRNA expression in normal, at-risk epithelium correlated with the presence of lung cancer." (PMID 22296774, 2012). "We sought to define the contribution of GRPR expression in bronchial epithelia to lung cancer risk in a larger case-control study where adjustments could be made for tobacco exposure and sex." (PMID 22296774, 2012). "Because GRPR expression in bronchial epithelia was associated with lung cancer, we hypothesized that for cases with detectable bronchial GRPR expression, survival would be reduced compared to cases without detectable GRPR expression." (PMID 22296774, 2012). "Lung cancer cases positive for GRPR bronchial expression were significantly younger than cases negative for GRPR expression, which supports the role of GRPR bronchial expression as conferring lung cancer risk." (PMID 22296774, 2012). "Further, gastrin releasing peptide receptor (GRPR) can cause growth stimulation in lung cancers and may be activated at an earlier stage in women who are exposed to tobacco smoke, either actively or passively." (PMID 21572841, 2009).
lung carcinoma (continued). "One study found that GRPR was more highly expressed in female than male non-smokers, and that in smokers, it was found at lower levels of tobacco exposure in women than in men, suggesting that female smokers’ two copies of GRPR could contribute to lung cancer susceptibility." (PMID 37370722, 2023). "In order to determine whether GRPR expression differed by tumor clinical and/or pathological characteristics, we tested for association between tumor characteristics and bronchial GRPR expression in lung cancer cases." (PMID 22296774, 2012). "When lung cancer cells, containing GRPR’s, are antagonized by GRPR antagonists, such as BW2258U89 or PD176252, proliferation is reduced." (PMID 41007372, 2025). "Despite advances in surgical intervention, radiotherapy, and multimodal treatments, lung cancer incidence continues to rise, and GRPR overexpression is found in 68% of adenocarcinoma cases in NSCLC." (PMID 39768218, 2024). "In lung cancer cells, antagonist peptides of gastrin-releasing peptide receptors (GRPR) can be used to decorate lipid-based vesicles for targeted delivery." (PMID 38167116, 2024). "PD176252 inhibited the binding of GRP/bombesin to GRPR and blocked the ability of the ligand to elevate cytosolic calcium levels and c-fos mRNA in lung cancer cells NCI-H1299, NCI-H345 and H1299." (PMID 29262666, 2017). "GRPR has been found to be highly expressed in patients with lung cancer induced by nicotine, which stimulates cell proliferation, contributing to tumorigenesis." (PMID 29207642, 2017). "Gastrin-releasing peptide receptor (GRPR) is differentially expressed on the surfaces of various diseased cells, including prostate and lung cancer." (PMID 26577829, 2015). "Similar to our previous findings of persistent bronchial GRPR expression after tobacco cessation, we detected bronchial GRPR expression in the majority of former smoking lung cancer cases." (PMID 22296774, 2012). "The proportion of GRPR positive actively smoking cancer-free control subjects was similar to the proportion of actively smoking lung cancer cases." (PMID 22296774, 2012). "Our primary finding was the observed increased expression of GRPR in normal bronchial epithelia in lung cancer cases compared to cancer-free controls." (PMID 22296774, 2012). "Among never and former smokers, lung cancer patients more frequently had detectable GRPR expression while the frequency of detected GRPR mRNA was similar for actively smoking lung cancer cases and controls." (PMID 22296774, 2012). "We evaluated GRPR mRNA levels in histologically normal bronchial epithelial cells from 224 lung cancer patients and 107 surgical cancer-free controls." (PMID 22296774, 2012). "Additionally, the activation of GRPR was found to enhance the survival of lung cancer cells exposed to tyrosine kinase inhibitors (TKIs)." (PMID 38279185, 2024). "The expression of GRPR in lung cancer has been extensively studied." (PMID 38279185, 2024). "Wang and colleagues exploited functionalized hybrid PAMAM dendrimers to target GRPR-positive lung cancer and, likewise, they showed very promising results, including selective absorption in the HEL-299 lung cancer cell line and beneficial retention in tumors in vivo after intratumoral injection." (PMID 38067350, 2023). "Gastrin-releasing peptide receptor (GRPR) is another transmembrane protein, a G protein-coupled receptor, which is highly overexpressed in many types of cancer ranging from pancreatic cancer, glioma, and lung cancer." (PMID 33532673, 2021). "In this study we explored whether surface engraftment of a GRPR antagonist peptide could be used to target GRPR expressing lung cancer cells for the purposes of enhanced liposome delivery to lung cancer." (PMID 31921534, 2019). "Additionally, gastrin-releasing peptide receptor (GRPR) was also identified as an important target candidate of DSCR9, and diseases that associated with GRPR include lung cancer and prostate adenocarcinoma." (PMID 29351810, 2018).
lung carcinoma (continued). "GRPR is overexpressed in lung cancers and in head and neck squamous cell carcinoma (HNSCC)." (PMID 22296774, 2012). "We have previously reported elevated levels of GRPR mRNA in lung cancers and HNSCC." (PMID 22296774, 2012). "GRPR expression in non-cancerous bronchial epithelium was significantly associated with the presence of lung cancer in never and former smokers." (PMID 22296774, 2012). "The GRPR pathway is known to interact with the EGFR pathway in lung cancer cells by increasing the release of EGFR ligands such as amphiregulin, which could act to further promote cancer in never smokers who develop EGFR mutations." (PMID 22296774, 2012). "The association between GRPR bronchial expression and lung cancer among never smokers and former smokers was significant even after controlling for the effects of age, sex, and pulmonary function." (PMID 22296774, 2012). "Our group previously reported that bronchial epithelium expression of GRPR, which encodes the gastrin-releasing peptide receptor (GRPR), was associated with a diagnosis of lung cancer in female never smokers." (PMID 22296774, 2012). "In order to assess the association of subject characteristics with GRPR expression independent of cancer, a stratified analysis by case status was performed separately for the lung cancer case and control populations." (PMID 22296774, 2012). "We found the GRPR expression by sex interaction to not be significantly associated with lung cancer among never smokers in a multiple logistic regression model also containing age, sex and pulmonary function (P = 0.94)." (PMID 22296774, 2012). "In lung cancer GRPR and its ligand are involved in autocrine growth stimulation." (PMID 22296774, 2012). "Though we did not assess the epidermal growth factor receptor (EGFR) mRNA or protein expression in bronchial epithelial cultures, we speculate that increased GRPR expression contributes to lung cancer through EGFR-dependent and/or -independent mechanisms." (PMID 22296774, 2012). "Of the 224 lung cancer cases evaluated, 158 (71%) had GRPR expression in bronchial cells." (PMID 22296774, 2012). "Among former smoking lung cancer cases, bronchial GRPR expression may be aberrantly maintained following cessation of smoking, or similar to never smoking lung cancer cases, bronchial GRPR expression may reflect risk that is independent of tobacco use." (PMID 22296774, 2012). "Therefore, this study presents important revisions to our previous understanding of the role of GRPR in lung cancers arising in females and males; this study supports a similar role for bronchial GRPR mRNA expression and lung cancer risk for both females and males." (PMID 22296774, 2012). "Therefore, this study did not support our previous hypothesis that GRPR expression among women contributed to their increased lung cancer risk." (PMID 22296774, 2012). "Importantly, even after controlling for the effects of possible confounding by age, sex, and tobacco use, GRPR expression in non-cancerous mucosal tissues was significantly associated with lung cancer among never and former smokers and appeared to confer similar risk to both sexes." (PMID 22296774, 2012). "Though the specific cause of GRPR expression in never smoking lung cancer cases is unknown, we posit that bronchial GRPR expression may reflect an inherent or conferred risk factor that can be best observed in the absence of the more potent risk factor of tobacco use." (PMID 22296774, 2012). "GRPR and GRP are involved in an autocrine stimulation loop in lung cancer and HNSCC, and GRPR expression has been shown to be positively regulated by GRP." (PMID 22296774, 2012). "GRPR knockdown significantly inhibited lung cancer cell invasion, while no changes were observed in cell proliferation following GRPR depletion." (PMID 39768218, 2024).